APOB (apolipoprotein B)
Diseases named in the same sentence as APOB in open-access papers (continued):
Sharing a sentence is not in itself a finding about the gene and the disease.
steatosis (continued). "In the mild steatosis group, the BMI value and serum levels of ALT, ALP, UA, TC, APOB, and insulin were higher than that in control group (all P < 0.05)." (PMID 34986792, 2022). "Excess alcohol intake will inhibit apolipoprotein B (ApoB) and VLDL synthesis, resulting in the inability to smoothly release hepatic lipids, resulting in steatosis." (PMID 34290612, 2021). "The levels of serum ApoB were reported to be negatively correlated with the HCV viral load and steatosis." (PMID 34492079, 2021). "Previous studies have shown that NAFLD patients with simple steatosis exhibit higher hepatic expression of MTTP and ApoB, as well as higher serum VLDL levels." (PMID 33187321, 2020). "The results also revealed that both IL-6 and IL-10 concentration was reduced in the liver, accompanied by lower apoB protein expression and resulting TAG accumulation (steatosis)." (PMID 20920329, 2010). "Moreover, in the male APOB and APOB/HSP groups, the increasing levels of steatosis and hepatocyte ballooning led to significantly higher NAS as well." (PMID 40855499, 2025). "APOB−/− and MTTP−/− mutant organoids constitute a natural steatosis organ model and can be maintained in long-term culture at levels that maintain a stable level of steatosis." (PMID 37175830, 2023). "Since AMPK is known to phosphorylate PGC1α, which also increases MTTP and ApoB expression, our results suggest that GSEE could exert its anti-steatosis effect by regulating multiple processes such as lipid export, synthesis, and consumption in mouse livers." (PMID 33187321, 2020). "TXNDC5, which has been associated with regulation of ER stress, is influenced by hepatic fat and might play an important role in apolipoprotein B (APOB) control and steatosis development." (PMID 25526565, 2014). "Moreover, hepatic fat influences TXNDC5, which has been linked to the regulation of ER stress, and may be crucial for the control of apolipoprotein B (APOB) and the development of steatosis." (PMID 38138960, 2023). "We then investigated liver graft mRNA gene expression of PNPLA3 and APOB, involved in Ld-MaS and VLDL metabolism, and of genes involved in cholesterol hepatic metabolism according to the presence and the predominant type of steatosis in the pre-ischemia biopsy before LT." (PMID 34198853, 2021). "Lack of this functionality may contribute to the development of steatosis, but it is not likely to cause the decrease of serum TG, VLDL, and ApoB secretion that was observed in the UBXD8-LKO mouse." (PMID 25970332, 2015). "However, whether HCV-induced ApoB degradation contributes to steatosis has not been clarified." (PMID 34492079, 2021). "In the group of rats that were taking tomato juice (with and without steatosis), the genes involved in β-oxidation as well as the thrombospondin receptor (CD36) were positively regulated, and apolipoprotein B (APOB) and lipoprotein lipase (LPL) were negatively regulated." (PMID 31330977, 2019).
breast carcinoma (46 papers, 2010 to 2026). "Regarding our finding that ApoB was important for the prediction of myocardial ischemic risk in breast cancer patients, the role of ApoB in CVDs and cancers was explored at first." (PMID 40678973, 2025). "The somatic mutation patterns of ERGs in breast cancer highlighted APOB, LRP1, and VPS13B as the top 3 frequently mutated genes." (PMID 39792732, 2025). "This study will help screen high‐risk patients with breast cancer for the comorbidity occurrence of myocardial ischemia diseases by evaluating ApoB and HER2 levels, together with the routine indicators." (PMID 40678973, 2025). "For instance, APOB has been identified as a risk factor in breast cancer and has been implicated in promoting the risk of intraocular metastasis in breast cancer patients." (PMID 38243282, 2024). "Ultimately, the study explored the association of APOB gene expression with breast cancer recurrence rates, immune cell infiltration, and drug response." (PMID 38243282, 2024). "In a population-based prospective cohort study involving men, we found a positive association between ApoB and cancer risk, while female breast cancer risk showed an inverse relationship with ApoB." (PMID 39193372, 2024). "Mutations in the APOB gene, including 7673CT as well as 12,669 GA, are significantly associated with an increased risk of breast cancer and are frequently present in menopausal females." (PMID 38067270, 2023). "One study found that breast cancer risk was inversely associated with ApoB (HR = 0.92, 95%CI 0.86–0.99)." (PMID 35986413, 2022). "The SNP rs693 in the APOB gene increased the risk of breast cancer and aortic stenosis among Chinese subjects." (PMID 36145636, 2022). "In women, apoB was inversely related to breast cancer risk (HR: 0.92; 95% CI: 0.86–0.99), whereas in both genders, apoA-I was negatively linked to lung cancer risk (HR: 0.88; 95% CI: 0.80–0.97)." (PMID 31936330, 2020). "Low apoA/apoB ratio has been associated with increased lung and colorectal cancer risk, but reduced breast cancer risk in females." (PMID 31936330, 2020). "The levels of APOB are positively associated with the risk of colorectal cancer, breast cancer, lung cancer." (PMID 29728103, 2018). "Moreover, several studies have reported an association between elevated lipid levels (e.g., LDL, ApoB, Lpa) and an increased risk of breast cancer in patients." (PMID 40678973, 2025). "Notably, the different roles of ApoB in the risk prediction of cardiovascular comorbidities of breast cancer and benign breast tumor patients were uncovered in this study." (PMID 40678973, 2025). "Moreover, ApoB plays a pivotal role in cholesterol transportation to peripheral tissues and is associated with breast cancer development." (PMID 40678973, 2025). "Specifically, breast cancer patients with APOB mutations exhibited higher infiltration levels of CD8 + T cell, Macrophage, activated NK cell, and T follicular helper cells, with corresponding log2 fold changes of 0.915524732, 0.564052222, 0.738113493, and 0.446620369, respectively." (PMID 38243282, 2024). "However, the relationship between mutated APOB, immune infiltration, and response to immunotherapy in breast cancer remains poorly characterized." (PMID 38243282, 2024). "Furthermore, enhanced APOB expression is considered a statistically significant risk factor for the intraocular metastasis of breast cancer." (PMID 38067270, 2023). "Similarly, serum apoB levels were negatively associated with breast cancer risk in another nested case–control study." (PMID 31936330, 2020). "In a large-scale prospective cohort study, the investigators found that high circulating ApoB could increase the risk of CRC in men but reduce the risk of breast cancer in women." (PMID 31956353, 2020). "Furthermore, there are reports linking increased apoB levels with a higher risk for lung and colorectal cancer, as well as low apoB concentrations with a greater risk for breast cancer." (PMID 31936330, 2020).
breast carcinoma (continued). "Myocardial ischemia risk in breast cancer patients may evolve over a longer time frame, and a longer follow‐up duration would allow for a more comprehensive evaluation of the relationship between serum ApoB and HER2 levels and myocardial ischemia risk." (PMID 40678973, 2025). "We did observe a significantly lower median proportion of the apolipoprotein B mRNA editing catalytic polypeptide-like–related signature SBS2 in breast cancers, SBS6 in colorectal carcinoma, and SBS5 in HCC in the OM cohort compared with MSK." (PMID 40778578, 2025). "Further research studies should elucidate the underlying mechanisms linking serum ApoB and HER2 levels and myocardial ischemia risk in breast cancer patients, including investigating the molecular pathways associated with this relationship." (PMID 40678973, 2025). "The patients were divided into two groups based on the low and high expression levels of ApoB (n = 46 of ApoBlow and n = 98 of ApoBhigh group in breast cancer patients, n = 29 of ApoBlow and n = 21 of ApoBhigh group in benign breast tumor patients)." (PMID 40678973, 2025). "Taking these results above, we compared the roles of ApoB in breast cancer patients, benign breast tumor patients, and pooled patients together, and the role of breast cancer history in affecting the myocardial ischemia occurrence." (PMID 40678973, 2025). "While this study provides insights into the relationship between serum ApoB and HER2 levels and myocardial ischemia risk in breast cancer patients, it is important to acknowledge its limitations." (PMID 40678973, 2025). "By comparing the significance of ApoB in breast cancer patients versus benign breast tumor patients, it was observed that ApoB and HER2 were crucial predictors of myocardial ischemia in breast cancer patients compared to those with benign breast tumors." (PMID 40678973, 2025). "Comparisons of the baseline characteristics in the groups with low or high levels of apoB in breast cancer patients, n (%) or median(IQR)." (PMID 40678973, 2025). "WES analysis of the patient’s breast cancer sample revealed three unique nonsynonymous SNVs in the APOB, TBC1D32, and XAB2 genes." (PMID 38243282, 2024). "Other known driver genes that weren't identified by the pan-cancer analysis were identified, such as CBFB, CDH1, PTEN in breast cancer and APOB in the liver." (PMID 34997044, 2022). "This study aimed to investigate level fluctuations of serum biomarkers that are associated with cardiotoxicity risk, such as high-sensitivity C-reactive protein (hs-CRP) and apolipoprotein-B (Apo-B) in response to chemotherapy treatment for breast cancer." (PMID 34711013, 2021). "After adjusting for HDL-C and apoB/apoA-I ratio, breast cancer patients still had significantly lower apoA levels, thus highlighting a potential role of this apolipoprotein in breast cancer." (PMID 31936330, 2020). "As chemotherapy treatment significantly increased apoB levels in breast cancer patients, we investigated the effect of doxorubicin, cyclophosphamide and paclitaxel on apoB protein levels in HepG2 cells." (PMID 26807857, 2016). "Subsequent hierarchical clustering suggested that a number of those genes (including PPARG, FGF2, APOB, CRHBP, CETP, and RXRG) were significantly associated with breast cancer that appeared repeatedly in different GO-terms." (PMID 21059268, 2010). "We found that ApoB, age, and HER2 were the key factors responsible for disease incidence, which were identified as risk factors associated with the development of CVD in breast cancer patients." (PMID 40678973, 2025). "However, the unexpected protective effect of a high level of ApoB observed in our study aligns with previous findings in breast cancer research." (PMID 39193372, 2024). "The identification of mutated APOB as a potential biomarker for Herceptin and TKI resistance could be beneficial for breast cancer patients, as it would enable the prompt administration of immunotherapy." (PMID 38243282, 2024).
breast carcinoma (continued). "The positive association between ApoB and cancer risk in men, coupled with the inverse relationship in female breast cancer, suggests that hormonal and tissue-specific factors may modulate ApoB’s influence." (PMID 39193372, 2024). "Another study revealed that an increase in the APOB to APOA1 ratio is associated with an increase in the severity of breast cancer, but this was not statistically significant." (PMID 38067270, 2023). "For cardiovascular biomarkers, a cohort study found an inverse association between ApoB, but not ApoA and breast cancer risk." (PMID 36424572, 2022). "In addition, APOBEC3G (apolipoprotein B mRNA-editing enzyme, catalytic polypeptide-like 3G) is involved in RNA editing, and deletion in APOBEC3 gene has been correlated to breast cancer risk." (PMID 30922380, 2019). "Interestingly, the isoforms of the apolipoprotein B mRNA-editing enzyme catalytic polypeptide-like (APOBEC3A, APOBEC3B and APOBEC3H), implicated in breast cancer carcinogenesis, were also up-regulated." (PMID 25961742, 2015). "We demonstrated that ApoB and HER2 were potential factors in predicting the myocardial ischemia occurrence in breast cancer patients." (PMID 40678973, 2025). "For the baseline characteristic analysis in the breast cancer patients, a significant difference was found in age (p = 0.009), lipids (TC, TG, LDL, ApoB) (p < 0.001), and Atorvastatin administration (p = 0.033)." (PMID 40678973, 2025). "Univariate and multivariable Cox regression found that ApoB, age, and HER2 were significant factors responsible for the myocardial ischemia occurrence in breast cancer patients." (PMID 40678973, 2025). "In pancreatic cancer, APOA2, APOC1, APOC2, and APOJ have been described, while APOB was found in HCC, bladder, and breast cancer." (PMID 37628784, 2023). "Mechanistically, overexpression of APOB in MDA-MB-231 cells inhibits their growth and invasion by depleting the lipid supply to the breast cancer cells." (PMID 38283944, 2023). "Our gene network analysis indicated that two protein transporters including APOB and CLCA2 contribute in the breast cancer." (PMID 34236536, 2021). "It was observed that ApoB was more important in breast cancer patients, rather than in benign breast tumor patients, to predict the myocardial ischemia occurrence." (PMID 40678973, 2025). "APOB, previously identified as a candidate gene related to lipid abnormality, was proved significant in the incidence of CRC and lung cancer while APOA1 was correlated with the incidence of breast cancer." (PMID 34820194, 2021). "Serum levels of APOB could predict responses to NACT and relapse-free survival in advanced breast cancers patients." (PMID 34737677, 2021). "Results from another 12 breast cancer patients demonstrated a significant reduction in HDL-C and ApoA-I and an elevation in ApoB after the treatment of either doxorubicin and cyclophosphamide followed by paclitaxel or epirubicin, cyclophosphamide and 5-Fu followed by docetaxel." (PMID 27344180, 2016). "It is a member of the apolipoprotein B mRNA-editing enzyme, catalytic polypeptide-like editing complex family together with APOBEC3B, which was found to be a source of mutagenesis in many major cancer types, including breast cancer." (PMID 25505134, 2015). "Despite these constraints, we found a number of biologically meaningful, differentially expressed genes related to HIST1, HIST2 proteins, and some other such as PPARG, FGF2, APOB, CRHBP, CETP, and RXRG in breast cancer tissue compared to corresponding adjacent normal breast tissue." (PMID 21059268, 2010). "However, our MR study found a positive association between genetically predicted ApoA, but not genetically predicted ApoB and overall breast cancer liability." (PMID 36424572, 2022). "Our data demonstrated that ApoB and HER2 were potential factors in predicting the myocardial ischemia occurrence in breast cancer patients, rather than in benign breast tumor patients." (PMID 40678973, 2025).
breast carcinoma (continued). "This study demonstrated that ApoB and HER2 were potential factors in predicting the myocardial ischemia occurrence in breast cancer patients, rather than in benign breast tumor patients." (PMID 40678973, 2025).
dyslipidaemia (43 papers, 2010 to 2025). "The population-attributable coronary risk due to dyslipidaemia (defined as the ratio apoB/apoA-I) was almost double in some of these emerging economic regions compared with the European Union region." (PMID 24460800, 2014). "In individuals with DM, inflammation was mostly associated with higher levels of the pro-atherogenic lipids ApoB and VLDL-TG, aligned with established links between chronic inflammation, dyslipidaemia and elevated CVD risk." (PMID 40568317, 2025). "Hyperglycaemia itself impacts CVD risk by inducing dyslipidaemia, characterised by elevated LDLC, TG, ApoB and decreased HDLC levels." (PMID 40375303, 2025). "Abnormal cholesterol esterification rates in apoB-lipoprotein-depleted plasma (fractional esterification) and lipoprotein particle size result in dyslipidaemia." (PMID 35239727, 2022). "One of the first drugs developed for parenteral use in dyslipidaemia was mipomersen, an antisense oligonucleotide that targets apolipoprotein B (Apo B) mRNA and interferes with translation, thereby decreasing Apo B levels." (PMID 35890138, 2022). "Our findings therefore suggest that the measurement of ApoB should potentially be considered, especially for patients with atherogenic dyslipidaemia, since ApoB is more likely to be discordantly high in relation to LDL-C." (PMID 35054008, 2022). "Insulin has also been shown to directly increase the degradation of apoB which ameliorates dyslipidaemia." (PMID 29975702, 2018). "A considerable differentiation of the concentration data of lipids, apoB, and apoAI indicates that there were patients with dyslipidaemia and dyslipoproteinaemia characterized by elevated levels of atherosclerotic lipid and lipoprotein profiles." (PMID 26666260, 2015). "A low ratio of LDL-C/ApoB (reverse ApoB/LDL-C) has been reported to be the optimal indicator to detect dyslipidaemia among diabetic patients." (PMID 24093822, 2013). "This was accomplished by evaluation of the levels of the markers of dyslipidaemia, oxidative stress and inflammation; namely, apolipoprotein B (Apo B), NO and ferritin, respectively, in the study group." (PMID 22331247, 2012). "Most of these studies focus on standard measures of circulating lipids and lipoproteins, and in general, they show associations between ‘dyslipidaemia’, for example elevated plasma LDL-cholesterol or apolipoprotein B (apoB), and the severity of diabetic retinopathy." (PMID 27306616, 2016). "Apolipoprotein B levels signify the extent of dyslipidaemia." (PMID 22331247, 2012). "Decreased values of apoA-1 potentiated the impact of apoB at all levels of apoB (on average across apoB range: 40% increase in HR for MACE and 72% increase in HR for non-fatal MI), indicating that the apoB/apoA-1 ratio covers a broader range of persons with dyslipidaemia at risk than apoB alone." (PMID 34851955, 2021). "However, there has been an ongoing debate on whether apoB, or rather the apoB/apoA-I ratio, would be a more appropriate measure for estimating CHD risk associated with dyslipidaemia." (PMID 23359805, 2013). "Dyslipidaemia was primarily driven by DM, but more pro-atherogenic in TB-DM, with elevated VLDL and apolipoprotein B (ApoB)." (PMID 40568317, 2025). "A high prevalence of severe dyslipidaemia (>90th percentile) was identified, highest for small dense LDL-C (31.3%), apoB (30.4%), and LDL-C (30.3%)." (PMID 39598108, 2024). "The TULIP, ROSE, ROSE2 and OCEAN trials, performed in participants with dyslipidaemia, demonstrated significant reductions in LDL-C and apoB, whereas HDL-C was increased considerably after 12 or 8 weeks of medication." (PMID 38786974, 2024).